BRCA1 (BRCA1 DNA repair associated)
Diseases named in the same sentence as BRCA1 in open-access papers (continued):
Sharing a sentence is not in itself a finding about the gene and the disease.
breast cancer (continued). "In this report we have characterised familial non-BRCA1/2 tumours and evaluated routine immunohistochemical and pathological markers that could help us to further distinguish families carrying BRCA1/2 mutations from other breast cancer families." (PMID 15642173, 2005). "Hilakivi-Clarke has suggested that early estrogen exposure may reduce breast cancer risk by increasing the expression of tumor suppressor genes such as BRCA1, inducing differentiation of immature breast cells into more mature ductal structures in addition to stimulating epithelial growth." (PMID 15987426, 2005). "Similarly, ovarian ablation has been shown to reduce recurrence and mortality in breast cancer patients, and prophylactic oophorectomy has been shown to significantly reduce breast cancer incidence in high-risk women, including BRCA1 and BRCA2 mutation carriers." (PMID 16280052, 2005). "However, the probability of finding ATM and BRCA1 mutations in sporadic breast cancer is low." (PMID 15138484, 2004). "Even after researchers had identified a gene called BRCA1, which is associated with greatly increased risk of breast cancer, the implications of this gene for the breast cancer risk in the general population remained unknown for a long time because epidemiological studies were not carried out." (PMID 12875047, 2002). "For BRCA1/2 carriers, risk‐reducing salpingo‐oophorectomy (RRSO) is additionally recommended after childbearing to reduce ovarian and breast cancer risk." (PMID 41510186, 2026). "While over 75% of BRCA1-mutated and about 50% of BRCA2-mutated breast cancers exhibit a TNBC phenotype, only 10–20% of all TNBC cases are due to inherited (germline) BRCA mutations." (PMID 41602389, 2026). "BRCA1 and BRCA2 mutations are the most common mutations in breast cancer, conferring lifetime risks of approximately 72 and 69% by the age of 80 years, respectively." (PMID 41510186, 2026). "We next explored the expression of ELF3 in breast cancers in the TCGA and METABRIC databases to further investigate the association between ELF3 and BRCA1 and validate our previous analysis." (PMID 41498327, 2026). "Background/Objectives: Contralateral breast cancer (CBC) is a significant concern among breast cancer survivors, particularly in those with moderator-high penetrance germline mutations such as BRCA1, BRCA2, CHEK2, and ATM." (PMID 41976331, 2026). "Age to start routine annual MRI screening for BRCA1/2-positive women depends on personal and family history of breast or other cancers and age at first breast cancer diagnosis in the family." (PMID 41488281, 2026). "Among the group who entered the MRI-screening program, the age-adjusted HR for breast cancer mortality was 0.20 (95% CI: 0.10 - 0.43; P < 0.001) for women with BRCA1 and 0.87 (95% CI: 0.10 - 17.25; P = 0.93) for women with BRCA2 variants." (PMID 41488281, 2026). "Aggressive breast cancer subtypes, such as triple-negative breast cancer (TNBC) and tumors in BRCA1 germline mutation carriers, present significant clinical challenges." (PMID 41751865, 2026). "When stratified by breast cancer outcome, patients who developed breast cancer demonstrated elevated mean TC scores compared to those who remained unaffected, particularly within the BRCA1/2 subgroup." (PMID 41568159, 2026). "Considering her family history and her age at breast cancer diagnosis, we recommended her to undergo genetic counseling and BRCA1/BRCA2 genetic testing, however, she refused to do either." (PMID 41585001, 2026). "At the molecular level, DNMT1 overexpression promotes hypermethylation of tumor suppressor gene promoters (including ERα and BRCA1), which leads to their silencing and enhances breast cancer aggressiveness, particularly in ER-negative and HER2-positive tumors." (PMID 41602389, 2026). "According to our previous analysis, case #3 BRCA1 mutant carrier developed basal-like breast cancer, which was derived from LPs." (PMID 41498327, 2026).
breast cancer (continued). "In one study, 1,583 BRCA1 and 881 BRCA2 mutation carriers with unilateral breast cancer were enrolled in a tamoxifen prevention trial." (PMID 41488281, 2026). "Since most BRCA1 mutation carriers develop basal-like breast cancers, we next investigated the association between ELF3 and basal-like breast cancers." (PMID 41498327, 2026). "The highest lifetime risks of developing malignant disease due to inherited BRCA1 and BRCA2 mutations are observed in breast cancer, with rates of 70–80% and 50–60%, respectively." (PMID 40841483, 2026). "Reported lifetime breast cancer risks for women with LFS range up to 80–90%, surpassing the risk linked to BRCA1- and BRCA2-related hereditary breast cancer, whereas ESMO guidelines indicate a substantially lower lifetime risk of around 40%." (PMID 41528496, 2026). "In this study, we aimed to investigate the splicing impact of +2T variants in the breast cancer susceptibility genes ATM, BRCA1, and PALB2." (PMID 41230741, 2026). "Although poly (ADP-ribose) polymerase (PARP) inhibitors (PARPi) are approved for breast cancer, their clinical use is largely limited to the small subset of HER2-negative patients with germline BRCA1/2 mutations, and resistance is frequently observed." (PMID 41158759, 2026). "Compared to the sporadic group, triple-negative breast cancers were overrepresented among BRCA1 carriers (23.6% vs. 75.5%; p < .001), and family history of breast cancer was significantly more frequent among BRCA1, BRCA2, and PALB2 carriers (all p < .05)." (PMID 42252839, 2026). "Fifth, our study did not include data on high‐impact breast cancer variants, such as those located in BRCA1 and BRCA2, which limits a comprehensive examination of their potential influence on breast cancer risk." (PMID 40944570, 2026). "The prevalence of BRCA1 promoter methylation in sporadic breast cancer is variable, depending on the selected cohort, in particular the molecular subtype." (PMID 39392573, 2025). "In breast cancer, OlympiAD demonstrated olaparib’s benefit in prolonging PFS for HER2-negative, BRCA1/2-mutated metastatic patients, and EMBRACA confirmed similar efficacy for talazoparib." (PMID 40069561, 2025). "Mutations in genes like BRCA1 and BRCA2 are well known for significantly increasing the risk of breast cancer, particularly in hereditary cases." (PMID 40565055, 2025). "Individuals with pathogenic variants in the BRCA1 and/or BRCA2 genes face elevated risks of cancer, including a 70% lifetime risk of breast cancer and 40% lifetime risk of ovarian cancer." (PMID 40862808, 2025). "Expression of BARD1 and BRCA1 are upregulated by activation of the PI3K/Akt pathway in these resistant breast cancer cells." (PMID 39858015, 2025). "BRCA1 and BRCA2 germline mutation carriers had an increased cumulative risk of 72% and 69%, respectively to develop breast cancer by 80 years old." (PMID 40531958, 2025). "This is supported by recent studies in BRCA1-deficient mouse models, which indicate that luminal progenitors rather than actual stem cells are most likely the source of both BRCA1-related and basal-like breast cancers." (PMID 41283276, 2025). "BRCA1 and ESR1 gene mutations specifically cause breast cancer, while error in the CYP19A gene leads to cancers in the endometrium, ovaries, and thyroid." (PMID 41514592, 2025). "Here, reports of the significant disparities between groups in which patients diagnosed with breast cancer are offered and undergo testing for BRCA1/2 PGVs are reviewed." (PMID 40123843, 2025). "Combination of DDX3 and PARP inhibition has also reported to enhance sensitivity in BRCA1-proficient breast cancer." (PMID 40882371, 2025). "The biologic differences between BRCA1 and BRCA2-associated breast cancers have been well established in the literature, with data on PALB2 continuing to evolve." (PMID 40275390, 2025). "9b, 9j, and 9l (BRCA1 mimetics) can function as ERα corepressors in breast cancer cells, mimicking the activity of the BRCA1 protein." (PMID 40283136, 2025).
breast cancer (continued). "Combined with BRCA1/2, high-penetrance genes account for approximately 25% of hereditary breast cancers." (PMID 40243654, 2025). "This cohort study examines the prevalence of pathogenic or likely pathogenic variants in BRCA1 and BRCA2 in women with breast cancer in a racially and ethnically diverse population." (PMID 40952741, 2025). "For example, mutations in BRCA1/2, ATM and PALB2 are most associated with breast cancer; mutations in ATM and BRCA2 are commonly associated with prostate cancer; mutations in BRCA1/2 are commonly associated with ovarian cancer." (PMID 40192976, 2025). "The present study is based on an adherent analysis of the literature focused on genes deregulated by BRCA1 and BRCA2 mutations in breast cancer and modulated by treatments." (PMID 40136510, 2025). "The molecular pathway of cisplatin-induced apoptotic cell death for TNBC was revealed using triple-negative BRCA1-deficient breast cancer HCC1937 cells and triple-negative BRCA1 wild-type breast cancer MDA-MB-468 cells." (PMID 41226649, 2025). "A total of 4,752 young women with breast cancer were included in the present analysis, of whom 3,069 were BRCA1 carriers and 1,683 were BRCA2 carriers." (PMID 39993249, 2025). "Particularly relevant for basal-like breast cancer (BLBC) and BRCA1-associated breast cancers, studies show that ROS levels correlate with the expression and activity of the transcription factor aryl hydrocarbon receptor (AhR)." (PMID 39857438, 2025). "Spatial transcriptomics has revealed that the pre-neoplastic mammary microenvironment is remodeled in BRCA1/2 mutation carriers, and that germline variants in BRCA1 and BRCA2 constitute major risk factors for specific breast cancer subtypes." (PMID 41463377, 2025). "Despite the limitation of having only five BRCA1 mutant cell lines available in CCLE breast cancer panel, we found that these BRCA1-mutant cell lines, out of 43, exhibited significantly lower DepMap scores compared to BRCA1 wild-type cell lines." (PMID 39844055, 2025). "Repression of SNAI2 transcription by BRCA1 is a critical point in the regulation of EMT in breast cancer cells." (PMID 41345200, 2025). "The presence of BRCA1 and BRCA2 mutations in breast cancer patients has significant implications in treatment decisions, primarily due to the distinct biological characteristics of these tumors and their response to specific therapies." (PMID 41568010, 2025). "The detailed analysis using the STRING database discovered functional associations of DEGs changes in the molecular pathways related to breast cancer with somatic monoallelic BRCA1 inactivation." (PMID 40870889, 2025). "While BRCA1 and BRCA2, which occur in approximately 1/400 individuals, are well-known genes contributing to a high risk of breast cancer, CS which occurs in 1/200,000 is less well known." (PMID 41180948, 2025). "This strategy is particularly effective in BRCA1/2-mutated, HR-positive, HER2-negative breast cancer." (PMID 41514640, 2025). "Mutations in BRCA1 and BRCA2 account for the majority of hereditary breast cancer cases and approximately 5 – 10% of all cases." (PMID 40800071, 2025). "Here, we treated the BRCA1 exon 11 mutant SUM149PT breast cancer cells and their complemented derivative expressing wild-type BRCA1 (SUM149PT + BRCA1) with the PARPi olaparib for 1 h, a previously established condition that promotes ssDNA gap formation." (PMID 40127955, 2025).
breast cancer (continued). "A history of breast cancer was observed in 55 patients (78.6%), and 47 patients (67.1%) underwent BRCA1/2 genetic testing at our institution." (PMID 40862027, 2025). "In breast cancer, tamoxifen-resistant cell lines express significantly higher levels of both BRCA1 and BARD1, diminishing the cytotoxic impact of chemotherapy." (PMID 41009605, 2025). "Many studies indicate that BRCA1/2-related tumors benefit more from chemotherapy than sporadic breast cancers." (PMID 40405286, 2025). "Triple-negative breast cancers are likely to be BRCA1 mutation positive, while HER2 amplification is uncommon in BRCA1 and BRCA2 mutation carriers." (PMID 39885374, 2025). "In particular, the loss of function of breast cancer 1 (BRCA1) and breast cancer 2 (BRCA2) is a predisposing factor for developing not only ovarian, pancreatic and breast cancers, but also prostate cancer." (PMID 40002869, 2025). "This study identifies a new ubiquitin modification pathway that regulates BRCA1 protein stability during cell cycle, and shows that its dysregulation in tumors is associated with features of BRCA-mutated breast cancer." (PMID 41359628, 2025). "This global study provides evidence on the different clinical behavior of breast cancer in young BRCA1 and BRCA2 carriers." (PMID 39993249, 2025). "For example, published guidelines recommend that patients with BRCA1/2 PGVs undergo bilateral oophorectomies to prevent ovarian cancer and regular magnetic resonance imaging to screen for breast cancer." (PMID 40123843, 2025). "Although PARP inhibitors have shown therapeutic benefit in BRCA1-mutant breast cancers, particularly in advanced stages, their effectiveness is often compromised by acquired resistance and suboptimal tumor suppression." (PMID 41148817, 2025). "It was also shown that there was a correlation between PARP2 and BRCA1/2 in the luminal B subgroup, indicating that those breast cancer patients can receive Anti-HER2 Monoclonal Antibodies as therapeutic drugs available in the clinic at present." (PMID 40141415, 2025). "This presents an opportunity for further combination therapy in breast cancer targeting both RANKL and progesterone in BRCA1 mutation carriers." (PMID 39941709, 2025). "Conversely, those with BRCA1/2 mutations and high serum OPG levels have been found to have a significantly decreased risk of breast cancer." (PMID 39941709, 2025). "The two major highly penetrant genes for breast cancer, BRCA1 and BRCA2, were identified in 1994 and 1995, respectively." (PMID 40770660, 2025). "Splicing dysregulation has emerged as a novel hallmark of breast cancer, with oncogenic splicing variants of HER2, ER, BRCA1, AIB1, and other tumor- and metabolism-related genes linked to heightened malignancy, poor prognosis, and treatment resistance." (PMID 40867231, 2025). "Nonetheless, resistance to PARP inhibitors or platinum chemotherapy in BRCA1 mutant metastatic breast cancer has been found." (PMID 41155174, 2025). "One of the most common genetic risk factors for ovarian cancer includes germline mutations in Breast Cancer gene 1 and 2 (BRCA1 and BRCA2, or BRCA1/2)." (PMID 41471359, 2025). "Although PVs have been reported across all exons of the BRCA1 and BRCA2 genes, variation hotspots highly associated with the development of breast cancer have been identified." (PMID 40071159, 2025). "For females ≥18 years with a GPV in BRCA1, BRCA2 or PALB2, a referral to the very high-risk breast cancer screening (VHRS) programme or equivalent should be made at the time of diagnosis." (PMID 41159931, 2025).
breast cancer (continued). "As expected, BRCA1-mutated UWB1.289 ovarian cancer and HCC1937 breast cancer cells displayed significant sensitivity to Olaparib." (PMID 39994444, 2025). "Here, we identify the structure-specific endonuclease SLX1 as a key regulator of HR and a determinant of Olaparib sensitivity in BRCA1-intact breast cancer." (PMID 41373774, 2025). "For comparison, we analyzed a cohort of BRCA1-positive breast cancer patients with ages at onset ranging from 39 to 57 years (n = 84)." (PMID 41374957, 2025). "In our study of 309 affected BRCA1/2 and PALB2 carriers with operable breast cancer, the receipt of chemotherapy following an index breast cancer diagnosis was 70% overall but varied from 57% in BRCA2 carriers to upwards of 80% in BRCA1 and PALB2 carriers." (PMID 40275390, 2025). "Currently, olaparib is approved for BRCA1/2 mutated HER2-negative metastatic breast cancer, and talazoparib is approved for BRCA1/2 mutated advanced breast cancer." (PMID 40978060, 2025). "Approximately 20–25% of hereditary breast cancer cases harbor germline mutations in the BRCA1 or BRCA2 genes, which are key breast cancer susceptibility loci." (PMID 41373619, 2025). "A strong association between the risk of breast cancer and family history was found for ATM, BRCA1, BRCA2, CHEK2, and PALB2 P/LP variant carriers." (PMID 39858629, 2025). "Initial analyses of BRCA1 carriers from HBOC families of the Breast Cancer Linkage Analysis Consortium had also suggested an increase in uterine cancer risk." (PMID 39400928, 2025). "This study aimed to identify the prevalence and mutation spectrum of the BRCA1 and BRCA2 germline mutations among 120 unselected series of Brunei breast cancer patients." (PMID 40531958, 2025). "Altogether, study results point to the role of FABP4 in breast cancer progression and should be further evaluated as a prognostic biomarker in breast cancer with a dysfunctional or reduced amount of BRCA1 protein." (PMID 40870889, 2025). "To further characterize the anti-tumor immune response in Brca1‐mutant breast cancer, we analyzed the lymph nodes, which represent the primary sites of T cell activation and priming." (PMID 41208884, 2025). "Further analyses have investigated potential distinctions between BRCA1- and BRCA2-associated breast cancers." (PMID 41463210, 2025). "Specifically, multiple breast cancer clusters in BRCA1 and BRCA2 are associated with relatively higher risks of breast cancer and relatively lower risks of ovarian cancer." (PMID 40007994, 2025). "From our analysis, only a minority of genes complied with the criteria: 69 and 10 genes in BRCA1 and BRCA2 mutated breast cancers, respectively, and 10 and 9 genes in BRCA1 and BRCA2 mutated ovarian cancers, respectively." (PMID 40647506, 2025). "Bilateral mastectomy, particularly in patients with BRCA1 or BRCA2 mutations, has been shown to increase overall survival and reduce breast cancer risk by over 85%." (PMID 40806826, 2025). "Using several breast cancer cohorts, we find that our classifier has a similar performance to other alternatives that detect BRCA1/2‐defective tumours." (PMID 40260608, 2025). "In preclinical models and patient samples of ovarian and breast cancer, including ascite metastases and in situ carcinomas, reduced DNA damage-induced nuclear RAD51 is positively associated with BRCA1 or BRCA2 gene defects and patient response to PARPi." (PMID 40830526, 2025). "In breast cancer, both BRCA1 and BRCA2 levels were significantly lower in TT compared with NAT (0.7378-fold change, p < 0.0001, and 0.6822-fold change, p < 0.0001, respectively)." (PMID 41373491, 2025).